CASP9 (caspase 9)
Diseases named in the same sentence as CASP9 in open-access papers (continued):
Sharing a sentence is not in itself a finding about the gene and the disease.
HIV-1 infection (3 papers, 2014 to 2025). The type species of lentivirus and the etiologic agent of acquired immunodeficiency syndrome (AIDS). "There was an inversely proportional link between total cellular ATP, which was used as marker of enhanced oxidative stress and hence a surrogate measure of cellular viability, and caspase 9 activation during HIV-1 infection of cardiomyocytes." (PMID 25329893, 2014). "Hence, we investigated the activation of caspase-3/7 and caspase-9 to assess the impact of AR extracts and Shatavarin IV in HIV-1 infection." (PMID 39507335, 2024).
kidney damage (3 papers, 2012 to 2024). "We evaluated the renal cell death by focusing on the RNA expression of apoptosis indicators Bcl-2, Caspase-9, and biomarkers of nephropathy (NGAL, KIM-1)." (PMID 33933022, 2021).
liver fibrosis (3 papers, 2017 to 2023). "Curcumin suppresses the NF-kB activity in CCl4-induced liver fibrosis, and it promotes cell death through activation of caspase 3 and caspase 9, as well as the altering nuclear shape and phosphotidylserine expression." (PMID 36985782, 2023). "We measured the expressions of Bax, Bcl-2, Caspase 3, and Caspase 9, which are all involved in apoptosis, to determine the anti-apoptotic activities of geniposide in CCl4-induced liver fibrosis." (PMID 34899328, 2021).
mesothelioma (3 papers, 2019 to 2023). A usually malignant and aggressive neoplasm of the mesothelium which is often associated with exposure to asbestos. "In the ceRNA networks, GAS1RR, AXIN2, AC017104.1, RASSF8-AS1, CGN, MIR4458HG, has-miR-125b-5p, LINC01105, and CASP9 were significantly associated with overall survival in mesothelioma." (PMID 31681739, 2019). "Based on co-expression patterns between ceRNA and immune cells, it was found that has-miR-582-5p, CASP9, dendritic cell rest, ANIX2, T cell CD8, and T cell CD4 memory rest may be associated with mesothelioma bone metastasis." (PMID 36439509, 2022). "Notably, based on the co-expression patterns between ceRNAs and Immune cells, we found that the hsa-miR-582-5p, CASP9, dendritic cells resting, ANIX2, T cells CD8, and T cells CD4 memory resting might be associated with the mesothelioma bone metastasis." (PMID 31681739, 2019). "AXIN2, CASP9, CGN, RASSF8-AS1, and MIR4458HG were highly expressed in mesothelioma compared to some other types of cancer." (PMID 31681739, 2019). "The integrative analysis of genomics and the clinical profiles using the cBioPortal suggested that AXIN2, CASP9, CGN, RASSF8-AS1, and MIR4458HG were highly expressed in mesothelioma compared to some other types of cancer." (PMID 31681739, 2019). "AXIN2, CASP9, CGN, RASSF8-AS1, and MIR4458HG were expressed in various mesothelioma cell lines but not in immune cells biomarkers." (PMID 31681739, 2019).
ovarian tumor (3 papers, 2007 to 2024). "Furthermore, activation of caspase-9, -3 and PARP was also observed in Ad-mda7-treated ovarian tumor cells but not in normal cells." (PMID 17274815, 2007).
retinal edema (3 papers, 2020 to 2023). "Stronger protection in eyes treated with the caspase-9 inhibitor suggest that caspase-9 signaling is a more critical target for treating retinal edema and capillary ischemia in RVO." (PMID 37449272, 2023). "Our results suggest that Astro Casp9 loss did not ameliorate retinal swelling, indicating that Astro Casp9 is not an active participant in the development of retinal edema." (PMID 36347836, 2022).
retinal vein occlusion (3 papers, 2020 to 2023). An occlusion of the retinal vein. "Since both caspase-9 inhibition and VEGF neutralization have been associated with improvements in retinal blood flow, we examined the development of retinal ischemia following induction of retinal vein occlusion." (PMID 37449272, 2023). "Here we show that activation of endothelial caspase-9 after hypoxia-ischemia is a critical event in subsequent dysfunction of the blood-retina barrier, using a panel of interrelated ophthalmic in vivo imaging measures in a mouse model of retinal vein occlusion (RVO)." (PMID 32576823, 2020).
retinoblastoma (3 papers, 2022 to 2025). A malignant tumor that originates in the nuclear layer of the retina. "The uHRF1-mediated PI3K/Akt signaling pathway downregulates the bcl-2/Bax expression ratio and promotes caspase-9 expression, which can inhibit the proliferation of retinoblastoma cells and promote apoptosis." (PMID 35656341, 2022). "Western blot results showed that the expression levels of caspase-8, caspase-9, caspase-3, and cleaved PARP increased in a concentration-dependent manner after the treatment of retinoblastoma cells with xanthatin." (PMID 40309730, 2025). "Meanwhile, hsa-miR-486-3p inhibits retinoblastoma cell growth by regulating the target gene ECM1, and hsa-miR-7641 regulates the apoptotic marker caspase-9 and anti-apoptotic marker BCL2, establishing them as oncogenic miRNAs." (PMID 37233676, 2023).
Salmonella Infections (3 papers, 2015 to 2024). Infections with bacteria of the genus SALMONELLA. "We transduced Cas9 expressing Gsdmd–/–;Bid–/–;Mlkl–/–;Casp3–/–;Casp7–/–;Casp9–/– iBMDMs with a whole-genome single guide RNA (sgRNA) library and stringently enriched for sgRNAs that promoted cell survival after Salmonella infection by repeating the infection and selection procedure three times." (PMID 32735843, 2020). "Our findings demonstrate that Salmonella infection altered the MNV response, preventing DNA fragmentation, PARP cleavage and blockade of caspase 9- and 3 cleavage events." (PMID 26658916, 2015).
small cell lung carcinoma (3 papers, 2010 to 2017). Small cell lung cancer (SCLC) is a highly aggressive malignant neoplasm, accounting for 10-15% of lung cancer cases, characterized byrapid growth, and early metastasis. "The HDAC inhibitor FR901228 could downregulate the expression of Bcl-2 and Bcl-XL, and activate caspase-9 and caspase-3 in small cell lung cancer cell lines." (PMID 26075388, 2015). "In small-cell lung cancer, OPN induced CisPt resistance by blocking caspase-9- and caspase-3-dependent apoptosis." (PMID 28611294, 2017).
systemic lupus erythematosus (3 papers, 2014 to 2021). An autoimmune multi-organ disease typically associated with vasculopathy and autoantibody production. "As presented in this work, GM extract attenuates lupus-associated cardiac apoptosis in lupus-prone mice by down-regulating TNF-α/TNF-α receptors and Fas/FADD and reducing amounts of activated caspase-9, Bax, activated caspase-8 and activated caspase-3." (PMID 25985203, 2015). "Our previous studies demonstrated that the disease activity of systemic lupus erythematosus (SLE) is positively associated with the mitochondrial membrane APO2.7 level of CD19+ cells, but negatively associated with MAVS and caspase-9 levels, which collectively indicate a mitochondrial pathway." (PMID 33800867, 2021). "This study aimed to explore the role of apoptosis initiators, caspase-9, caspase-10, mitochondrial anti-viral signaling protein (MAVS), and interferon regulatory factor 7 (pIRF7), in patients with systemic lupus erythematosus (SLE)." (PMID 25370148, 2014).
tongue cancer (3 papers, 2021 to 2024). A malignant neoplasm affecting the tongue. "The induction of caspase-9 activity was found in both tongue cancer cell lines after exposure to all compounds tested." (PMID 34201116, 2021). "In addition, bufalin acts on human tongue cancer cells; the protein levels of caspase-3 increase after 2 days, and caspase-9 is expressed after 3 days." (PMID 38268819, 2024).
type 2 diabetes (3 papers, 2016 to 2019). "On the other hand, the ratio of Bax to Bcl-2, the caspase-3 and caspase-9 mRNA levels and the number of apoptotic cells were increased in the livers of type 2 diabetic mice, which were prevented by BAIBA." (PMID 26907958, 2016).
acute pancreatitis (2 papers, 2017 to 2021). An acute inflammatory process that leads to necrosis of the pancreatic parenchyma. "In this study, we found that deletion of XIAP promotes cerulein+LPS-induced activation of caspase-3 and caspase-9, resulting in increased apoptosis, decreased necrosis and reduced severity of acute pancreatitis in vivo." (PMID 28300832, 2017).
amyotrophic lateral sclerosis (2 papers, 2023 to 2025). Amyotrophic lateral sclerosis (ALS) is a neurodegenerative disease characterized by progressive muscular paralysis reflecting degeneration of motor neurons in the primary motor cortex, corticospinal tracts, brainstem and spinal cord. "UCDA’s glycine conjugate glycoursodeoxycholic acid (GUDCA) alters mitochondria dynamics and apoptosis by reducing caspase-9 levels in motor neuron-like cells used in amyotrophic lateral sclerosis studies." (PMID 41373461, 2025). "CASP3, CASP9, tumor necrosis factor (TNF), and Bcl-2 were shown to be major contributory genes in connection with flavonoid action, amyotrophic lateral sclerosis (ALS), the epithelial cell apoptotic process, and hypoxia." (PMID 37446564, 2023).
anaplastic astrocytoma (2 papers, 2021 to 2023). "The strongest functional genetic association between caspase-9 and cancer is a stop-gain mutation at R65, which results in a catalytically inactive short isoform of caspase-9, and may cause increased susceptibility to development of anaplastic astrocytomas consistent with Li-Fraumeni-like syndrome." (PMID 34305609, 2021). "The results obtained showed an increase in caspase 7 activity in sorafenib-treated anaplastic astrocytoma cells, as well as after combination with LY294002, which was correlated with a boost in caspase 9 activity." (PMID 38067099, 2023).
Ascites (2 papers, 2018 to 2020). Accumulation of fluid in the peritoneal cavity (between the layers of the peritoneum that lines the abdomen). "IHC showed that LC-3 and Beclin-1 expression levels were increased in the re-ascites group; in contrast, CASP-9 and c-CASP-3 expression levels were reduced." (PMID 29549251, 2018).
astrocytoma (2 papers, 2015 to 2019). "The RCR-1 astrocytoma cell line contains high levels of extracellular adenosine, promoting apoptosis mediated by A1 receptor-stimulated caspase-9/-3 activation." (PMID 26491983, 2015).
autoimmune disease (2 papers, 2021 to 2023). A disorder resulting from loss of function or tissue destruction of an organ or multiple organs, arising from humoral or cellular immune responses of the individual to their own tissue constituents. "Gene association studies suggest potential caspase-9 involvement with multiple cancers, autoimmune disorders, and neurological disease." (PMID 34305609, 2021). "Recent studies have shown that altered activity or expression of CASP9 was involved in a variety of malignancies and autoimmune diseases." (PMID 37291547, 2023). "Studies reporting altered levels of caspase-9 in autoimmune disease." (PMID 34305609, 2021).
Behcet disease (2 papers, 2020 to 2021). A chronic, relapsing, multisystemic vasculitis characterized by mucocutaneous lesions, as well as articular, vascular, ocular and central nervous system manifestations. "In particular, our mechanistic understanding of caspase-9 signaling in lumbar disc disease, cardiovascular disease, and Behcet’s disease are limited to phenomenological observations." (PMID 34305609, 2021). "Increased caspase-9 expression has also been reported in Behcet’s disease, a multisystem disorder of unknown etiology that is driven by endothelial inflammation." (PMID 34305609, 2021). "Biochemical evidence links caspase-9 with immunodeficiency, sepsis, and Behcet’s disease." (PMID 34305609, 2021).
brain injury (2 papers, 2021 to 2022). Acute and chronic (see also brain INJURIES, CHRONIC) injuries to the brain, including the cerebral hemispheres, CEREBELLUM, and brain STEM. "A significant increase in total caspase-8 and caspase-9 levels (p < 0.001) corresponding with activation of the selected apoptotic factors within the first 7 days after brain trauma was observed." (PMID 35665033, 2022). "Increasing NAAG levels by inhibiting GCPII activity 1 day before ischemia in rats also resulted in decreased caspase-9 and caspase-3 activity; moreover, an increase in cleaved caspase-3 level in a mouse model of traumatic brain injury was attenuated in the GCPII knockout mice." (PMID 33763176, 2021).
cardiomyopathy (2 papers, 2019 to 2021). A disease of the heart muscle or myocardium proper. "Differential expression of caspase-9 neoepitopes and downstream effector caspases in different forms of cardiomyopathy suggests that multiple caspase-9 signaling pathways are involved in these disorders." (PMID 34305609, 2021). "To date, studies of caspase-9 involvement in heart disease have relied primarily on biochemical detection methods, and we still do not know the cellular localization of caspase-9 in these pathologies, limiting our understanding of the signaling pathways regulating caspase-9 in cardiomyopathy." (PMID 34305609, 2021).
Cirrhosis (2 papers, 2012 to 2016). A chronic disorder of the liver in which liver tissue becomes scarred and is partially replaced by regenerative nodules and fibrotic tissue resulting in loss of liver function. "In this study, host genes involved in apoptosis such as BCL212 and PDCD1 showed down-regulation in initial fibrosis and significant up-regulation in cirrhosis, whereas, expression levels for CASP9 and EMP1 genes were high at initial stage and were down-regulated in cirrhosis stage." (PMID 22397681, 2012).
colon adenocarcinoma (2 papers, 2021 to 2024).
Crohn disease (2 papers, 2019 to 2023). A gastrointestinal disorder characterized by chronic inflammation involving all layers of the intestinal wall, noncaseating granulomas affecting the intestinal wall and regional lymph nodes, and transmural fibrosis. "In this study, we evaluate the expression of the BAX, BCL2, CASP3 and CASP9 genes at the mRNA level in the peripheral blood lymphocytes of patients with ulcerative colitis and Crohn’s disease during the disease process." (PMID 31159239, 2019). "Expression of the genes BAX, BCL2, CASP3 and CASP9 was assessed at the mRNA level in the peripheral blood lymphocytes of patients with ulcerative colitis and Crohn’s disease relative to the healthy subjects." (PMID 31159239, 2019).
cutaneous melanoma (2 papers, 2006 to 2025). A primary melanoma arising from atypical melanocytes in the skin. "Our study revealed that DIOS significantly suppressed the proliferation and migration of cutaneous melanoma cells, reduced the levels of Bcl-2, and increased the protein expressions of Cleaved caspase-9, Cleaved caspase-3, and Cleaved PARP." (PMID 39844566, 2025).
dementia (2 papers, 2012 to 2024). Loss of intellectual abilities interfering with an individual's social and occupational functions. "Altogether these data indicate that caspase-9 is excessively activated in Danish dementia mice." (PMID 23217200, 2012). "Our study suggests that inhibiting caspase-9 activity may be a viable therapeutic option in human dementias." (PMID 23217200, 2012). "Based on these dissimilarities it could be argued that FDDKI and Tg2576 mice represent dementias caused by distinct pathogenic mechanisms, involving either sAPPβ/β-CTF and caspase-9 or Aβ and caspase-3, respectively." (PMID 23217200, 2012).
diabetic cardiomyopathy (2 papers, 2022 to 2024). Diabetic cardiomyopathy is a disorder of the heart muscle in people with diabetes. "In another study on diabetic cardiomyopathy, it was reported that NKILA was highly expressed in high sugar-induced AC16 cells, and apoptosis protein markers such as BAX, CASP3, and CASP9 were increased, while anti-apoptosis protein BCL-2 was inhibited." (PMID 39184397, 2024). "In conclusion, SCU may alleviate diabetic cardiomyopathy by upregulating the autophagy-related factors (Beclin-1, LC3-I, and LC3-II) and downregulating apoptosis-related factors (caspase-3, caspase-8, caspase-9, caspase-12, Bax, and Cyt-C) of cardiomyocytes." (PMID 35571612, 2022).
disc degeneration (2 papers, 2015 to 2021). "However, without further experimental evidence, it remains unclear whether caspase-9 activity drives disc degeneration, or whether increased caspase-9 activation is a downstream correlate of tissue injury." (PMID 34305609, 2021).
HCMV infection (2 papers, 2020 to 2022). "The caspase-3 and caspase-9 activities were obviously increased under HCMV infection." (PMID 35359726, 2022).
hypothyroidism (2 papers, 2018 to 2021). Abnormally low levels of thyroid hormone. "This caspase can activate mitochondrial-released caspase 9, and both activate effector caspase 3, which we firmly believe happens in hypothyroidism-induced neuronal death in the hippocampus." (PMID 29743975, 2018).
infertile (2 papers, 2021). "A direct association between increased sperm damage caused by ROS and high levels of cytochrome C, caspase 9, and 3 was demonstrated in the study by Soderquist and colleagues which showed positive apoptosis in infertile men." (PMID 34401644, 2021).
liposarcoma (2 papers, 2019 to 2022). A usually painless malignant tumor that arises from adipose tissue. "In the 93T449 human liposarcoma, AZD1208 at 20 μM was highly cytostatic (cytotoxic) but not apoptotic, as evidenced by cell death with no increase in any apoptotic marker measured: sub G1 phase, nuclear DNA fragmentation or caspase-9/3 activation." (PMID 30654529, 2019).
lumbar disc disease (2 papers, 2021 to 2023). "CASP9 polymorphisms have been linked with various cancers, neurological disorders, autoimmune pathologies and lumbar disc disease." (PMID 34305609, 2021). "A combination of genetic and histologic studies have identified an association between caspase-9 and lumbar disc disease (LDD)." (PMID 34305609, 2021). "Interestingly, CASP9 has already been known as a multimodal therapeutic target with diverse cellular expression in human disease, and CASP9 polymorphisms have been linked with various cancers, neurological disorders, autoimmune pathologies, and lumbar disc disease." (PMID 36911522, 2023). "Caspase-9 upregulation has been associated with the progression of myopathy in slow-channel syndrome (SCS, a myasthenic disorder caused by mutations in acetylcholine receptors) and in intervertebral disk degeneration in lumbar disc disease (LDD)." (PMID 34305609, 2021).
lymphoid leukaemia (2 papers, 2019 to 2022). "In both myeloid and lymphoid leukaemia cell lines, all combination treatments caused a synergistic increase in CASP-9 and CASP-3 gene expression when compared to the vehicle control and drugs alone (P ≤ 0.05)." (PMID 35614109, 2022). "In contrast, emodin and rhein when used with cisplatin or cyclophosphamide only increased in caspase 9 activity in lymphoid leukaemia cells (P ≤ 0.05); whereas cis-stilbene combined with cisplatin increased in caspase 8 and 9 activity, but only in lymphoid leukaemia cell lines (P ≤ 0.05)." (PMID 31360305, 2019).